ARHGEF39 (Rho guanine nucleotide exchange factor 39)
Description:
Promotes cell proliferation.
Synonyms: C9orf100; FLJ14642; XGEF
Tractability: Antibody: UniProt places it where antibodies can reach, with high confidence; its Gene Ontology location is reachable by antibodies, with high confidence. PROTAC: ubiquitination databases record sites on it.
Gene: Protein-coding gene on chromosome 9 (35,658,875 to 35,675,866, reverse strand). Ensembl gene ENSG00000137135.
Subcellular location: Cell membrane
Pathways (Reactome):
Signal Transduction: G alpha (12/13) signalling events; NRAGE signals death through JNK; RAC1 GTPase cycle
Gene Ontology:
Molecular function: protein binding; guanyl-nucleotide exchange factor activity
Biological process: positive regulation of cell migration
Cellular component: plasma membrane
Genetic constraint (gnomAD): Loss-of-function variants: 45 observed, 45.64 expected, observed/expected ratio (o/e) 0.99, 90% interval 0.77 to 1.26. The upper end of that interval is the gene's LOEUF score, 1.26, which puts it in group 5 of 6, group 1 being the genes least tolerant of losing a copy. Missense variants: 411 observed, 417.65 expected, observed/expected ratio (o/e) 0.98, 90% interval 0.91 to 1.07. Synonymous variants: 164 observed, 163.07 expected, observed/expected ratio (o/e) 1.01, 90% interval 0.88 to 1.14.
Homologues: Orthologues: chimpanzee ARHGEF39 (99% identical), macaque ARHGEF39 (98% identical), pig ARHGEF39 (89% identical), guinea pig ARHGEF39 (88% identical), mouse Arhgef39 (87% identical), rat Arhgef39 (87% identical), rabbit ARHGEF39 (81% identical), dog ARHGEF39 (79% identical), zebrafish arhgef39 (50% identical), tropical clawed frog arhgef39 (41% identical), Caenorhabditis elegans exc-5 (20% identical), Caenorhabditis elegans frm-3 (8% identical). Paralogues in human: FGD2 (25% identical), FGD5 (25% identical), FGD6 (25% identical), FGD4 (24% identical), FARP2 (23% identical), FGD3 (23% identical), FGD1 (23% identical), FARP1 (21% identical), ECT2L (20% identical), FRMD7 (7% identical).
Diseases named in the same sentence as ARHGEF39 in open-access papers:
ARHGEF39 is named in the same sentence as 19 diseases in open-access papers, as found by Europe PMC text mining. Sharing a sentence is not in itself a finding about the gene and the disease. The quoted sentences say what the papers report.
gastric cancer (5 papers, 2019 to 2024). A primary or metastatic malignant neoplasm involving the stomach. "ARHGEF39 has been found to be associated with human hepatocellular carcinoma, gastric cancer and nonsmall cell lung cancer." (PMID 33231603, 2020). "ARHGEF39, which is a Dbl-family guanine nucleotide exchange factor, is implicated in the development of a range of malignancies such as gastric cancer 28 and non-small cell lung cancer." (PMID 31632503, 2019). "Overexpress of ARHGEF39 promotes gastric cancer cell proliferation and migration through the Akt signaling pathway." (PMID 38463168, 2024). "The overexpression of ARHGEF39 has also been identified in various human malignancies, including non-small cell lung cancer, gastric cancer, and hepatocellular carcinoma." (PMID 36313444, 2022). "In gastric cancer, ARHGEF39 has been revealed to promote cancer cell growth and migration through the Akt signaling pathway." (PMID 33231603, 2020). "ARHGEF39 has been indicated to play a potential carcinogenic role in the development of human hepatocellular carcinoma, gastric cancer and non-small cell lung cancer." (PMID 33231603, 2020). "ARHGEF39 promotes gastric cancer cell proliferation and migration via Akt signaling pathway." (PMID 36241648, 2022).
non-small cell lung carcinoma (3 papers, 2019 to 2022). A group of at least three distinct histological types of lung cancer, including non-small cell squamous cell carcinoma, adenocarcinoma, and large cell carcinoma. "ARHGEF39 promoted non-small cell lung cancer proliferation by stimulating the Rac1-P38-ATF2 signaling pathway and increasing the expression of Cyclin A2, Cyclin D1, and MMP2." (PMID 33231603, 2020).
hepatocellular carcinoma (2 papers, 2020 to 2022). A malignant tumor that arises from hepatocytes. "According to the research results, ectopic expression of ARHGEF39 is conducive to the proliferation of hepatocellular carcinoma cells by affecting the G2/M phase." (PMID 33231603, 2020).
lung adenocarcinoma (2 papers, 2022 to 2025). A carcinoma that arises from the lung and is characterized by the presence of malignant glandular epithelial cells. "Finally, seven copper death genes related to lung adenocarcinoma were screened out, including ARHGEF39, EFCC1, SERPIND1, INSL4, ANLN, RHOV and CCL20." (PMID 36313444, 2022).
lung carcinoma (2 papers, 2022). "A recent study has added that ARHGEF39 is necessary for RAC1 activation during migration of lung cancer cells in response to growth factors, but this study did not investigate any potential activation of RHOA." (PMID 35959104, 2022). "For instance, it was recently reported that the A549 lung cancer cell line was dependent on the GEFs ARHGEF39, FARP-1, and TIAM-2 while the MDA-MB-231 and GFP-HER2-BM cells have a different GEF compliment and express Vav." (PMID 36861094, 2022). "In hepatocellular and lung cancer, increased expression of ARHGEF39 has been reported as a prognostic factor for tumour size and patient survival." (PMID 35959104, 2022). "Another previous study exploring the interaction partners of ARHGEF39 identified RAC1, but not RHOA (or CDC42) in a pulldown assay from lung cancer cells overexpressing ARHGEF39." (PMID 35959104, 2022).
Anxiety (1 paper, 2024). Intense feelings of nervousness, tension, or panic often arise in response to interpersonal stresses. "Interestingly, some of the linear dose-response DEGs have been implicated in transmission and plasticity (GRIN2A, GAD2), depression and antidepressant effect (DDIT4, GAD2) anxiety and stress responses (ADCYAP1R1), WNT signalling (FRZB), neurogenesis (ARHGEF39) and hippocampal volume (ANKRD37)." (PMID 39055655, 2024).
bladder cancer (1 paper, 2019). "LAG1 longevity assurance homolog 2 (LASS2) and Polypeptide N-acetylgalactosaminyltransferase 1 (GALNT1) were present in bladder cancer patients, whereas Rho guanine nucleotide exchange factor 39 (ARHGEF39) and Forkhead box protein O3 (FOXO3) were only found in controls." (PMID 30769831, 2019).
clear cell renal cell carcinoma (1 paper, 2020). "We attempted to explore the effect of Rho guanine nucleotide exchange factor 39 (ARHGEF39) on the phenotypes of clear cell renal cell carcinoma (ccRCC) cells and the underlying mechanism." (PMID 33231603, 2020).
dysplasia (1 paper, 2020). A usually neoplastic transformation of the cell, associated with altered architectural tissue patterns. "In addition, Facio-Genital Dysplasia-5 (FGD5) is an important paralog of ARHGEF39 and it has been revealed that the FGD5 plays a role in VEGF-mediated angiogenesis and regulates the VEGF/PI3 kinase/Akt pathway." (PMID 33231603, 2020).
language disorder (1 paper, 2022). A category of disorders characterized by an impairment in the development of an individual's language capabilities, which is in contrast to his/her non-verbal intellect. "RHOA activity, cell de-adhesion, cell division, and neural progenitor cells present new avenues to explore how changes in ARHGEF39 may contribute to neural development and to language disorder." (PMID 35959104, 2022).
liver cancer (1 paper, 2024). An epithelial or non-epithelial malignant neoplasm that arises from the liver. "Integrative analysis of gene expression differences in liver cancer further highlights three genes: ARHGEF39, UBE2C and DQX1." (PMID 38463168, 2024). "Previous literature has proposed that ARHGEF39 may act as an oncogene in the progression of liver cancer, and thus represents a potential prognostic indicator and therapeutic target for this disease." (PMID 38463168, 2024). "Among them, ARHGEF39 and UBE2C have been reported in the literature as potential oncogenes involved in the development of liver cancer." (PMID 38463168, 2024). "Our analysis has identified three potential oncogenes, ARHGEF39, UBE2C, and DQX1 of liver cancer." (PMID 38463168, 2024).
prostate carcinoma (1 paper, 2020). A carcinoma that arises from epithelial cells of the prostate gland. "However, ARHGEF39 was found to be absent in extracellular vesicles in urine samples from prostate cancer patients, while it was detected in noncancer samples." (PMID 33231603, 2020).
cancer (5 papers, 2014 to 2023). A tumor composed of atypical neoplastic, often pleomorphic cells that invade other tissues. "Most studies on ARHGEF39 have investigated its role in cancer, while the developmental and neurobiological roles of ARHGEF39 have received limited attention, leaving open questions about its contribution to neurodevelopmental phenotypes and disorders." (PMID 35959104, 2022). "Furthermore, overexpression of ARHGEF39 leads to increased proliferation, migration, and invasion of cancer cells." (PMID 35959104, 2022). "Expression of ARHGEF39 has been shown to promote cell proliferation in cancer cells." (PMID 35959104, 2022). "LASS2 and GALNT1 were only present in samples from cancer group, meanwhile ARHGEF39 (in the array named Chromosome 9 open reading frame 100 (C9orf100)) and FOXO3 were absent in cancer group and could be detected in control group." (PMID 24458310, 2014). "LASS2 and GALNT1 were present in cancer patients, while ARHGEF39 and FOXO3 were found only in non-cancer urinary vesicles." (PMID 24458310, 2014). "Of the genes expressed, cancer exosomes consistently contained GALNT1 and LASS2 transcripts while lacking FOXO3 and ARHGEF39 expression, with the opposite being true for the healthy samples." (PMID 33803085, 2021).
tumor (2 papers, 2020 to 2024). "Through previous work, we learned that ARHGEF39 is a new member of the DBL protein family of GEFs, which are notably associated with tumor migration." (PMID 33231603, 2020). "Rho guanine nucleotide exchange factor 39 (ARHGEF39) is a new member of the Dbl-family of guanine nucleotide exchange factors (GEFs), which are pivotal catalysts of GTPases and are markedly associated with tumor metastasis." (PMID 33231603, 2020). "The data showed that ARHGEF39 mRNA expression was notably correlated with the pathologic stage (p = 0.003) as well as T stage (p = 0.019), but there was no statistical relevance with Grade of tumor, Pathologic-N, Pathologic-M, gender and age (p > 0.05)." (PMID 33231603, 2020).
neurodevelopmental disorder (1 paper, 2022). A behavioral and cognitive disorder with onset during the developmental period that involves impaired or aberrant development of intellectual, motor, or social functions. "It would be of interest to study the molecular pathways and biological processes mediated by ARHGEF39 in these cell populations to understand its role in neurodevelopment, particularly since changes in Rho GTPase activation have emerged as a molecular hub in various neurodevelopmental disorders." (PMID 35959104, 2022).
ARHGEF39 also shares sentences with these, for which no sentence is quoted: arterial hypertension (1 paper); depression (1); Intellectual disability (1); speech delay (1).